NTN1 (netrin 1)
Diseases named in the same sentence as NTN1 in open-access papers (continued):
Sharing a sentence is not in itself a finding about the gene and the disease.
cancer (continued). "In addition, combining chemotherapeutic agents and netrin-1 interference potentiates cancer cell death." (PMID 28710382, 2017). "Netrin-1, an extracellular guidance cue critical for neuronal axon path-finding, has been reported to play an important role in cell invasion and migration in several types of cancers." (PMID 28710382, 2017). "Netrin-1, a multifunctional secreted protein, is up-regulated in cancer and inflammation." (PMID 28174720, 2016). "Increased netrin-1 expression has been observed in many types of advanced cancers." (PMID 27034160, 2016). "Our data show that netrin-1 is strongly upregulated in most cancer subtypes." (PMID 24647424, 2014). "However, since netrin-1 is strongly overexpressed in various cancer entities, it has been presented as a pluripotent tumor biomarker independent of the grade of malignancy or tumor subtype." (PMID 24647424, 2014). "Researches show that netrin-1 can activate PKC α after combination with its receptor, which may cause phosphorylation to promote cancer cell proliferation, and then restrain cell proliferation." (PMID 24528886, 2014). "As Netrin-1 is also known to control cell death and survival in numerous cancers, we will be further interested in whether Netrin-1 regulates thymocyte survival." (PMID 24369474, 2013). "It is therefore interesting to speculate that the netrin-1 upregulation may be a survival mechanism employed by cancer cells in response to these drugs." (PMID 24293316, 2013). "In addition, netrin-1 is also shown to increase kidney epithelial proliferation and migration and cancer development and progression." (PMID 22046354, 2011). "Briefly, netrin-1 (NTN1), the DCC family of receptors and the human UNC5 ortholog comprise part of a signaling pathway that is involved in the regulation of apoptosis, and whose dysregulation has been implicated in human cancers." (PMID 20187943, 2010). "Furthermore, we found that the expression of NTN1 and its receptors in several cancers, including BLCA, KIRC, READ, and COAD, was closely associated with tumor-infiltrating immune cells such as CD4 + T cells, CD8 + T cells, macrophages, neutrophils, and dendritic cells." (PMID 41407823, 2025). "Thus, YAP can induce several UNC5 receptors and their ligand NTN1 in YAPoff cancers." (PMID 39172021, 2024). "Although the Netrin-1 level in the peripheral system is changed widely in a large number of diseases, it might bear the potential as a biomarker in diseases of the similar type (such as cancer) or sharing a similar mechanism (such as inflammation)." (PMID 38638604, 2024). "Given the extreme complexity of tumour heterogeneity, we have not yet demonstrated whether the effect of N137 on tumour EMT is mediated by a direct effect of netrin-1 blockade on cancer cells or whether this effect is due to an indirect effect triggered by changes in the tumour microenvironment." (PMID 37532934, 2023). "In addition to its direct impact on cancer cells, netrin-1 inhibition may hence inhibit the crosstalk between pro-neoplastic CAFs and cancer cells, reducing malignant plasticity." (PMID 36499024, 2022). "However, Netrin-1 has been identified as a potential biomarker for tumorigenesis because regulation of the Netrin-1 status is found in multiple tissue-derived cancers." (PMID 34063230, 2021). "We propose that targeting SEMA3F and netrin-1 may be a promising strategy for cancer therapy." (PMID 30532711, 2018). "There is rising evidence that netrin-1 may also play a crucial role in carcinogenesis and metastasis in several cancer types through regaining its original involvement in angiogenesis in some cancer." (PMID 29854303, 2018).
cancer (continued). "We have shown for the first time that such a species-specific high throughput strategy is feasible in vivo using the CAM model and can lead to the discovery of tumor progression genes in cancer cells which are not expressed in vitro, such as NTN1 encoding netrin-1 or the chemokine CXCL4V1." (PMID 29662633, 2018). "Also the fact that NGF and AGM levels stay high seems realistic: NGF levels are higher in inflammation and some studies report that semaphorin 7A and netrin-1 levels are significantly elevated in patients subject to chemotherapy and some kinds of cancers, respectively." (PMID 26861829, 2016). "Furthermore, netrin-1 may constitute a promising target for future anti-cancer treatment approaches in brain metastases." (PMID 24647424, 2014). "Of interest, we describe here that the fraction of cancer that could show dependence receptor dependent apoptosis inhibition, may even be larger as many tumours treated with conventional chemotherapies may potentially upregulate netrin-1." (PMID 24293316, 2013). "Indeed, a high percentage of colorectal and metastatic breast cancers overexpress NTN1." (PMID 21789787, 2011). "While the role of NTN1/NEO1 signaling in neural development has been well-established, the effects of NEO1 activation on cancer cells remained largely unexplored." (PMID 40777309, 2025). "We found that NTN1, DCC, DSCAM, MCAM, and UNC5D were methylated in many cancers, of which UNC5D was the most prominent." (PMID 41407823, 2025). "Treatment with the NTN1 antibody decreased FAK phosphorylation, downregulated ZEB1 and SOX9, reduced Ki-67+ proliferating cancer cells, and also decreased PGP9.5+ and TH+ nerves." (PMID 40777309, 2025). "NTN1 inhibition also reduced VIM expression and increased E-cadherin expression in GFP-labeled mT4 cancer cells." (PMID 40777309, 2025). "Ntn1 KO reduces the features of EMT and cancer stemness and decreases innervation to extend the survival of KPC mice." (PMID 40777309, 2025). "We envisage, therefore, that the ability of Netrin-1, UNC5, and Integrin-αV/β5 to arrest growth in YAPoff cancers likely involves their physical interaction, although that remains to be demonstrated formally." (PMID 39172021, 2024). "Netrins are considered protumorigenic, but knockout and peptide/decoy receptor blocking assays reveal that in YAPoff cancers, UNC5B and Netrin-1 can cooperate with integrin-αV/β5 to mediate YAP-induced cytostasis." (PMID 39172021, 2024). "Deleted in colorectal cancer (DCC) and neogenin are receptors mediating attractive signaling by netrin-1, whereas Unc5 receptors are mediating repulsive signaling by netrin-1." (PMID 35743067, 2022). "Due to the close relationship between UNC5A and netrin-1, we explored the relationship between UNC5A and tumor immunity in cancers." (PMID 36551254, 2022). "We noticed an intriguing reciprocal relationship between the reported effects of netrin-1 and BMP signaling on several types of cancer cells." (PMID 33883596, 2021). "Netrin 1 (NTN1) and deleted in colorectal carcinoma (DCC) regulate midline zipper glia (MZG) organization during interhemispheric fissure (IHF) remodelling." (PMID 33871356, 2021). "Inhibition of DNA methylation by drugs such as dexitabine can restore the expression of NTN1 and DAPK1 in cancer cells with low expression of Netrin-137,38,68." (PMID 32251318, 2020). "The functional enrichment of DEGs in ESCC were mainly correlated with cell cycle, DNA replication, deleted in colorectal cancer (DCC) mediated attractive signaling pathway, and Netrin-1 signaling pathway." (PMID 31139019, 2019). "For instance, a repertoire of axon-guidance molecules (e.g. netrin-1, UNC5A, NEO1, RGMA) have been shown to be dysregulated in human cancers, including colorectal cancer." (PMID 29459716, 2018). "Results described in this manuscript propose that the inhibition of DNA methylation by drugs such as decitabine restores the expression of both NTN1 and DAPK1, in netrin‐1‐low cancer cells." (PMID 27378792, 2016).
cancer (continued). "Here we first unravel NTN1 and its receptor UNC5B as the key downstream targets of Naa10 in cancer cell line." (PMID 27910960, 2016). "The inhibition of DNA methylation by drugs such as decitabine restores the expression of both NTN1 and DAPK1 in netrin‐1‐low cancer cells." (PMID 27378792, 2016). "Netrin-1 and its receptor UNC5B play important roles in angiogenesis, embryonic development, cancer and inflammation." (PMID 24528886, 2014). "The search for the fraction of cancer patients who could be eligible for netrin-1 interference-based treatment during early clinical evaluation led us to examine the effects of conventional chemotherapeutic treatments on netrin-1 and netrin-1 receptors expression." (PMID 24293316, 2013). "The NTN1 and DCC mRNAs were quantified by real-time RT-PCR in normal, benign and cancer ovarian tissues." (PMID 21789787, 2011). "NTN1 directly increases PDAC cell growth, EMT, and cancer stemness through NEO1." (PMID 40777309, 2025). "Consistent with prior work showing that Netrin-3 promotes SCLC, we found that Netrin-1 but not Netrin-3 was induced following forced YAP expression in this cancer." (PMID 39172021, 2024). "Intriguingly, it was demonstrated that the nematode homologue of PGRMC1, VEM-1, physically interacts with C. elegans UNC-40, the nematode homologue of the mammalian cell surface receptor ‘deleted in colorectal cancer’ (DCC), which is one of the receptors mediating netrin-1 function." (PMID 39007013, 2024). "High NTN-1 signalling through UNC5B and DCC during tumorigenesis has been related to cancer cell proliferation and migration by up-regulation of the proto-oncogene YAP, a downstream signalling of the Hippo pathway, important in cell proliferation and apoptosis." (PMID 36831381, 2023). "Netrin-1 and its receptor DCC play an important role in different cellular processes such as cell adhesion, mortality, proliferation, cell survival, tissue organization, and cancer." (PMID 35008701, 2021). "Interaction of netrin-1 with the DCC receptor is critical in several cellular processes including cell survival, proliferation and migration of human cerebral endothelial cells, tissue organization, cardiac protection, angiogenesis and cancer." (PMID 29059224, 2017). "Since the altered signaling of both Netrin-1 and EGFR plays a widespread role in cancer, we examined whether the two proteins might be functionally connected." (PMID 27031829, 2016). "Although YAP-induced UNC5 and NTN mRNAs in multiple YAPoff cancer lines, and we confirmed that YAP or TEAD-VP64 induced UNC5B protein across multiple lines, we were unable to confirm whether other UNC5 proteins or NTN1 protein were induced in lines in which their mRNAs were upregulated." (PMID 39172021, 2024). "Considered for the cancer-promoting effect and an essential role in m5C modification, we focused on NSUN2, which might mediate the regulation of DIAPH2-AS1 on the expression of NTN1." (PMID 37037818, 2023). "Since dysregulated secretion of adipokines promotes cancer cell progression in adjacent tissues to adipose depots and NTN-1 has been reported to trigger cancer cell migration, we aimed to elucidate the role of ACM and NTN-1 in the modulation of tumour Caco-2 cell chemotaxis." (PMID 36831381, 2023). "Netrin-1 and its receptors have also been shown to play a role in neuronal plasticity that is involved in learning, memory, and in survival and progression of non-neuronal cells, most importantly cancer cells of the breast and colon." (PMID 36361539, 2022).
cancer (continued). "Interestingly, activation of NTN1 expression in GBM could also be promoted by NF-κB, in an indirect manner since it has been reported that this transcription factor induces the expression of SHH in cancer." (PMID 34361013, 2021). "Overexpression of Neo was observed in multiple types of human cancer, especially in aggressive cancers; and unlike DCC and UNC5, Neo enhanced the proliferation and motility of GC cells in an Ntn1 independent manner." (PMID 25909166, 2015). "In our study, netrin-1 was strongly expressed in brain metastases of different primary tumors with highest levels in brain metastases of NSCLC and carcinomas which were not otherwise specified." (PMID 24647424, 2014).
tumor (89 papers, 2005 to 2025). "Together, our data demonstrate that epithelial NTN1 promotes tumor-associated axonogenesis and early pancreatic tumorigenesis in vivo." (PMID 40777309, 2025). "The Kras mutation induces NTN1 secretion from the pancreatic epithelium, which increases tumor-associated sympathetic axonogenesis via nerve NEO1." (PMID 40777309, 2025). "In light of this model, imbalance in the netrin-1/receptor can be one of the underlying causes of tumor occurrence or escape, either by gain of netrin-1 expression, or by loss of receptors expression." (PMID 36136711, 2022). "This has been extensively described for the receptors DCC and UNC5B that bind netrin-1 and it has been shown that netrin-1 interference is associated with tumor growth inhibition in various models." (PMID 35883457, 2022). "NTN1—the gene that encodes netrin-1, acts as oncogene to confer a selective advantage for tumor cell survival by blocking DCC or UNC-5H-induced apoptosis." (PMID 33390926, 2020). "Tumor cells can turn the proapoptotic signalling off and maintain their survival by the loss of NTN1 receptors or by increasing its NTN1 production and autocrine secretion which promotes tumor growth and metastases in several animal models." (PMID 30923634, 2019). "Netrin-1 expression was positively associated with the cell proliferation marker Ki-67, tumor grade, and tumor malignancy." (PMID 28710382, 2017). "More recently, the malignant potential of secreted full-length netrin-1 has been extended to a truncated intranucleolar variant, ΔN-netrin-1, which also induces tumor cell growth." (PMID 24647424, 2014). "As the truncated nuclear or nucleolar ΔN-netrin-1 isoform has been linked to the regulation of cell proliferation in tumor cells, we tested our cohort for a potential correlation of nuclear netrin-1 and Ki67 proliferation index." (PMID 24647424, 2014). "Next, we investigated whether NTN1 promotes pancreatic carcinogenesis and tumor-associated axonogenesis in mouse models of PDAC." (PMID 40777309, 2025). "For example, NTN1 has a neuroprotective role in Parkinson’s patients, whereas, in colorectal tumors, apoptosis-dependent receptor deletion due to Netrin-1 receptor deficiency exacerbates tumor progression." (PMID 37345154, 2023). "Netrin-1 overexpression caused a subtle increase in tumor cell proliferation, which may explain this increase to some extent." (PMID 28069038, 2017). "In addition to the tumor cell-associated netrin-1 expression, also some stromal and endothelial cells were strongly netrin-1-positive." (PMID 24647424, 2014). "Proof-of concept studies, in vitro and in mice or chicken models, have shown that the silencing of netrin-1 by netrin-1 siRNA or interference with netrin-1–receptors interaction are associated with tumour cell death and with the inhibition of tumour growth and metastases." (PMID 24293316, 2013). "DCC was initially discovered as a tumor suppressor associated with an allelic deletion of chromosome 18 in human colorectal cancer but later experimental studies have demonstrated that DCC mediates the chemoattractive guidance effect of Netrin-1 on rat spinal commissural axons." (PMID 28245592, 2017). "We analyzed the correlation between the expression of NTN1 and its receptors and 28 types of tumor-infiltrating lymphocytes (TILs) using the TISIDB database." (PMID 41407823, 2025). "In the splenic injection model using mT4 cells, NTN1 blockade extended mouse survival and decreased tumor burden." (PMID 40777309, 2025). "In line with this, Ntn1 KO decreased tumor-innervating adrenergic neurons in the celiac ganglia, as assessed by retrograde tracing from the pancreas using Fast Blue." (PMID 40777309, 2025). "Treatment with the NTN1-neutralizing antibody improved mouse survival and decreased histological tumor areas in the Panc02 liver metastasis model as well." (PMID 40777309, 2025).